AKAP5 (A-kinase anchoring protein 5)
Description:
Multivalent scaffold protein that anchors the cAMP-dependent protein kinase/PKA to cytoskeletal and/or organelle-associated proteins, targeting the signal carried by cAMP to specific intracellular effectors. Association with the beta2-adrenergic receptor (beta2-AR) not only regulates beta2-AR signaling pathway, but also the activation by PKA by switching off the beta2-AR signaling cascade. Plays a role in long term synaptic potentiation by regulating protein trafficking from the dendritic recycling endosomes to the plasma membrane and controlling both structural and functional plasticity at excitatory synapses. In hippocampal pyramidal neurons, recruits KCNK2/TREK-1 channel at postsynaptic dense bodies microdomains and converts it to a leak channel no longer sensitive to stimulation by arachidonic acid, acidic pH or mechanical stress, nor inhibited by Gq-coupled receptors but still under the negative control of Gs-coupled receptors (By similarity). Associates with ORAI1 pore-forming subunit of CRAC channels in Ca(2+) signaling microdomains where it recruits NFATC2/NFAT1 and couples store-operated Ca(2+) influx to calmodulin and calcineurin signaling and activation of NFAT-dependent transcriptional responses.
Synonyms: AKAP79; AKAP75; H21
Tractability: Antibody: its Gene Ontology location is reachable by antibodies, with high confidence; UniProt places it where antibodies can reach, with medium confidence. PROTAC: its protein half-life has been measured.
Gene: Protein-coding gene on chromosome 14 (64,465,499 to 64,474,503, forward strand). Ensembl gene ENSG00000179841.
Subcellular location: Postsynaptic recycling endosome membrane; Cell projection, dendrite; Postsynaptic cell membrane
Subcellular location (Human Protein Atlas): Golgi apparatus; Cytosol; Plasma membrane
Pathways (Reactome):
Developmental Biology: ROBO receptors bind AKAP5
Metabolism: Glucagon-like Peptide-1 (GLP1) regulates insulin secretion
Neuronal System: Trafficking of AMPA receptors
Gene Ontology:
Molecular function: adenylate cyclase binding; calmodulin binding; glutamate receptor binding; protein binding; protein kinase A regulatory subunit binding; protein phosphatase 2B binding; scaffold protein binding; SH3 domain binding; beta-2 adrenergic receptor binding; GABA receptor binding; molecular adaptor activity; protein kinase A binding
Biological process: adenylate cyclase-inhibiting G protein-coupled receptor signaling pathway; calcineurin-NFAT signaling cascade; negative regulation of adenylate cyclase activity; positive regulation of endosome to plasma membrane protein transport; positive regulation of long-term synaptic potentiation; positive regulation of protein localization to plasma membrane; chemical synaptic transmission; positive regulation of calcineurin-NFAT signaling cascade; positive regulation of calcium ion import across plasma membrane; postsynaptic neurotransmitter receptor cycle; signal transduction; synapse assembly
Cellular component: cytoplasmic side of plasma membrane; membrane raft; postsynaptic recycling endosome; postsynaptic recycling endosome membrane; cytosol; dendrite; dendrite membrane; dendritic spine; excitatory synapse; plasma membrane; postsynaptic density; postsynaptic membrane; protein serine/threonine phosphatase complex
Genetic constraint (gnomAD): Loss-of-function variants: 5 observed, 15.06 expected, observed/expected ratio (o/e) 0.33, 90% interval 0.17 to 0.7. The upper end of that interval is the gene's LOEUF score, 0.7, which puts it in group 2 of 6, group 1 being the genes least tolerant of losing a copy. Missense variants: 385 observed, 476.38 expected, observed/expected ratio (o/e) 0.81, 90% interval 0.74 to 0.88. Synonymous variants: 135 observed, 167.19 expected, observed/expected ratio (o/e) 0.81, 90% interval 0.7 to 0.93.
Homologues: Orthologues: chimpanzee AKAP5 (99% identical), macaque AKAP5 (94% identical), pig AKAP5 (78% identical), dog AKAP5 (76% identical), mouse Akap5 (62% identical), rat Akap5 (60% identical), rabbit AKAP5 (54% identical).
Diseases named in the same sentence as AKAP5 in open-access papers:
AKAP5 is named in the same sentence as 26 diseases in open-access papers, as found by Europe PMC text mining. Sharing a sentence is not in itself a finding about the gene and the disease. The quoted sentences say what the papers report.
diabetes (4 papers, 2020 to 2023). "Since elevated glucose conditions predominate in diabetes, we propose this AKAP5-anchored P2Y11/AC5/PKA/CaV1.2 nanocomplex may be implicated in the onset of diabetic vascular complications." (PMID 33082339, 2020). "In dB/dB and HFD models of diabetes, the increase in L-type Ca2+ channel activity in cerebral vascular smooth muscle cells was attributed to activation of an unexpected AKAP5-anchored PKA signaling pathway leading to phosphorylation of the CaV1.2 subunit at S1928." (PMID 32594191, 2021). "Given that hyperglycemia is a major metabolic abnormality in diabetes, we propose that this AKAP5/P2Y11/AC5/PKA/CaV1.2 nanocomplex could be involved in the development of diabetic vascular complications." (PMID 33082339, 2020). "Results may identify potential new targets (e.g. AKAP5, AC5, S1928) for drug development to treat vascular complications during diabetes." (PMID 32594191, 2021). "For instance, NFATc3 activation, via an AKAP5-anchored calcineurin-dependent pathway, was found to mediate downregulation in the expression and function of BKCa β1 subunit, contributing to enhanced myogenic tone of cerebral arteries in a HFD model of diabetes." (PMID 32594191, 2021).
stomach adenocarcinoma (4 papers, 2020 to 2023). "AKAP5 is not widely linked to cancer in the literature, yet low AKAP5 expression was correlated with poor prognosis in some stomach adenocarcinomas." (PMID 32764426, 2020). "AKAP5 is high-expressed in non-mucin producing stomach adenocarcinoma (NMSA) and might modulate gastric carcinogenesis via the estrogen signaling pathway." (PMID 38025711, 2023). "Low expression of AKAP5 may be a potential molecular marker for predicting poor prognosis of non-mucin-producing stomach adenocarcinoma (NMSA) via regulating cholesterol homeostasis, estrogen response, glycolysis, notch signaling, and adipogenesis pathways." (PMID 36185624, 2022).
cardiac hypertrophy (3 papers, 2019 to 2025). "Research has demonstrated that ΔAKAP5, which incorporates the CaN inhibitory structural domain of AKAP5, inhibits isoproterenol (ISO)-induced cardiac hypertrophy in genetically modified mice." (PMID 40599813, 2025).
Anxiety (2 papers, 2010 to 2013). Intense feelings of nervousness, tension, or panic often arise in response to interpersonal stresses. "Adenylate cyclase 5 (AC5) is highly expressed in the striatum as is AKAP5 and AC5 KO mice show reductions in several anxiety like behaviors." (PMID 20428246, 2010). "AKAP5 Pro100Leu has thus far not been related to human anxiety, but has been shown to affect human aggression and anger, with Pro homozygotes showing higher physical aggression and lower anger control." (PMID 23383244, 2013).
breast carcinoma (2 papers, 2018 to 2024). "Interestingly, AKAP5, AKAP9, AKAP11 and AKAP12 is expressed at lower levels in the basal-like and, less prominently in HER2-enriched subtypes, the breast cancer subtypes with highest risk of recurrence." (PMID 29433456, 2018). "To address if GPR30, β1AR, MAGUKs, and AKAP5 also form a complex when expressed natively, we first identified that MCF7 breast cancer cells express all the proteins of interest." (PMID 38211639, 2024). "MCF7 breast cancer cells express GPR30, β1AR, MAGUKs, and AKAP5 in the plasma membrane, and co-immunoprecipitation revealed that these proteins exist in close proximity also under native conditions." (PMID 38211639, 2024).
epidermoid carcinoma (2 papers, 2011 to 2012). "We extended the studies from HEK293 cells to human epidermoid carcinoma A431 cells, again probing if overexpression of AKAP12 would impact the AKAP5-mediated Erk1/2 activation in response to β-adrenergic agonist." (PMID 21831305, 2011).
schizophrenia (2 papers, 2013 to 2024). A major psychotic disorder characterized by abnormalities in the perception or expression of reality. "While copy number variations of the AKAP5 gene have been implicated in the risk for schizophrenia and bipolar disorder, the Pro100Leu polymorphism has thus far not been associated with risk for major psychiatric disorders." (PMID 23383244, 2013).
Arrhythmia (1 paper, 2025). Any cardiac rhythm other than the normal sinus rhythm. "Although AC9 labeled few selective cardiac proteins, its proximity to AKAP5 and SNTA1 (and weak labeling of KCNQ1, SS = 0.5) is in accord with its roles in cardiac repolarization and inheritable arrhythmias." (PMID 40749829, 2025).
depression (1 paper, 2022). "These opposite roles in the biological processes of depression could be explain by the protein partner bound by AKAP5: the complex of AKAP5 with calcineurin inhibit the ASIC1a functions while the association with PKA promote ASIC1a activity." (PMID 36386166, 2022). "Conversely, the disruption of AKAP5 in E18 embryonic cortical neurons negatively affect the inhibition of ASIC1a -a ion channel known to be involved in neuropathologies including depression and whose pharmacologic inhibition has antidepressant-like effects." (PMID 36386166, 2022). "The scaffolding protein AKAP5 (also called AKAP150 in rodent species and AKAP79 on human) have a dual role in depression." (PMID 36386166, 2022).
Hyperglycemia (1 paper, 2020). An increased concentration of glucose in the blood. "Thus, AKAP5 could influence membrane potential-dependent and independent mechanisms to control arterial myocyte contractility upon chronic hyperglycemia." (PMID 33082339, 2020).
Hypertension (1 paper, 2024). The presence of chronic increased pressure in the systemic arterial system. "The scaffolding molecule AKAP150 (AKAP5 in human) is also associated with hypertension." (PMID 39731196, 2024). "Therefore, AKAP5 may be a promising target for hypertension by specifically modulating hypertensive signaling pathways." (PMID 39731196, 2024).
oral squamous cell carcinoma (1 paper, 2020).
cancer (4 papers, 2020 to 2025). A tumor composed of atypical neoplastic, often pleomorphic cells that invade other tissues. "In particular, there is limited information available regarding the involvement of SLC35E4, AKAP5, and RDH8 in malignancies; only a few bioinformatics studies have addressed their potential as prognostic predictors for cancer." (PMID 38561388, 2024).
tumor (3 papers, 2012 to 2023). "The reduced expression of genes involved in stabilization of adherence proteins (AKAP5, 9, 11 and 12) as well as increase expression of genes associated with poor prognosis and proliferation (AKAP3 and AKAP8) strongly underscores the involvement of AKAP genes during tumor growth and dissemination." (PMID 29433456, 2018).
neurological disorders (1 paper, 2016). "It is known that molecular changes in Akap5 levels disrupt cAMP organisation and PKA signalling in the hippocampus and induce neurological disorders including AD." (PMID 27708245, 2016).
AKAP5 also shares sentences with these, for which no sentence is quoted: alcohol dependence (1 paper); bipolar disorder (1); fibrosis (1); heart failure (1); metastatic tumors (1); neurodevelopmental disorder (1); neuronal ceroid lipofuscinosis (1); peripheral nerve injury (1); prostate carcinoma (1); psychiatric disorder (1); spinal cord injury (1).